NEAT1 (nuclear paraspeckle assembly transcript 1)
Diseases named in the same sentence as NEAT1 in open-access papers (continued):
Sharing a sentence is not in itself a finding about the gene and the disease.
melanoma (continued). "It turned out that NEAT1 was positively correlated with SMAD2 in melanoma tissues (n=18)." (PMID 33202380, 2020). "Now that previous literature has illustrated the participation of miR-200 family in EMT and SMAD2 is regarded as the subsequent effector of the TGF-β signaling pathway in EMT, it’s reasonable to infer that the NEAT1/miR-200b-3p/SMAD2 axis can regulate the EMT process of melanoma cells." (PMID 33202380, 2020). "In brief, it displayed that the NEAT1/miR-200b-3p/SMAD2 axis may promote melanoma by activating EMT and immune responses." (PMID 33202380, 2020). "Collectively, we have good reasons to believe that NEAT1/miR-200b-3p/SMAD2 signaling pathway may promote melanoma partly by immune regulation." (PMID 33202380, 2020). "In addition, NEAT1/miR-200b-3p/SMAD2 axis promoted melanoma progression by activating EMT signaling pathway and immune responses." (PMID 33202380, 2020). "Furthermore, the level of NEAT1 in various melanoma cell lines (A375, A875 and M14) was found to be higher than that of non-cancer cells as well." (PMID 33202380, 2020). "In accordance with previous studies, our work verified that NEAT1 was highly expressed in melanoma." (PMID 33202380, 2020). "Hence, we can deduce that the tumor promoting effects of the NEAT1/ miR-200b-3p/ SMAD2 signaling pathway in melanoma is partly attributed to the activation of EMT." (PMID 33202380, 2020). "Moreover, we proved it in vitro and in vivo that NEAT1 regulated the proliferation and invasion of melanoma cells as a sponge by directly binding miR-200b-3p." (PMID 33202380, 2020). "In other words, NEAT1 was found to promote melanoma tumors’ proliferation, migration, and invasion." (PMID 31462890, 2019). "It illustrates that NEAT1 was correlated negatively to miR-23 expression in human melanoma samples." (PMID 31462890, 2019). "Another lncRNA, nuclear paraspeckle assembly transcript 1 (NEAT1), promotes melanoma growth and invasion via the miR-495-3p–E2F3 axis, inhibiting miR-495-3p and inducing E2F3, which is known to promote proliferation." (PMID 41463281, 2025). "NEAT1 overexpression suppresses GNA inhibition on cell vitality and eliminates GNA-induced melanoma cell ferroptosis." (PMID 39267831, 2024). "Many lncRNAs have been proved to be oncogenes in melanoma, such as FOXD3-AS1, NEAT1, MALAT1 and MEG3." (PMID 34247598, 2021). "Considering the correlations among miR-200b-3p, SMAD2 and NEAT1, the aim of this study is to investigate biofunction of NEAT1/miR-200-3p/SMAD2 axis in melanoma and explore its potential as a novel biomarker and therapeutic target of melanoma." (PMID 33202380, 2020). "The NEAT1/miR-200b-3p/SMAD2 signaling pathway promotes the proliferation and invasion of melanoma cells by activation of EMT." (PMID 33202380, 2020). "These are: MALAT1, NEAT1, PCA3, BCAR4, lncRNA-ATB (CTD−2314B22.3) and the recently-discovered melanoma driver SAMMSON (RP11−460N16.1)." (PMID 28128360, 2017). "Moreover, NEAT1 overexpression counteracts GNA-mediated suppression of cell viability and prevents GNA-induced ferroptosis in melanoma cells." (PMID 39267831, 2024). "The levels of nuclear enriched abundant transcript 1 (NEAT1), miR-485-5p, and absent in melanoma 2 (AIM2) in CD4+ T cells were determined using real-time quantitative polymerase chain reaction (RT-qPCR)." (PMID 34696702, 2021). "In vitro and in vivo, we demonstrated that both NEAT1 and SMAD2 could promote the proliferation and invasion of melanoma cells, and these effects were reversed by up-regulating miR-200b-3p." (PMID 33202380, 2020). "To confirm the regulatory relationship between NEAT1 and miR-200b-3p, we analyzed their correlation by Pearson’s analysis and found a negative correlation between NEAT1 and miR-200b-3p in melanoma tissues (R= −0.7369, P<0.001)." (PMID 33202380, 2020).
melanoma (continued). "Hence, in this study, we selected 6 well-documented lncRNAs associated with metastasis including MALAT1, HOTAIR, NEAT-1, HULC, MEG-3, and UCA1 to evaluate their expression in primary melanoma and matched lymph node metastasis tissues." (PMID 23862139, 2013). "However, the relationship between miR-200b-3p and NEAT1 in melanoma has not been fully elucidated." (PMID 33202380, 2020).
myocardial infarction (21 papers, 2019 to 2025). Gross necrosis of the myocardium, as a result of interruption of the blood supply to the area, as in coronary thrombosis. "Of translational importance, genetic loss of Neat1 in vivo resulted in an impaired heart function after myocardial infarction highlighting its translational relevance." (PMID 31634682, 2019). "In acute myocardial infarction, silencing NEAT1 alleviates disease severity by suppressing ferroptosis via the miR-450 b-5 p/ACSL4 pathway." (PMID 41268533, 2025). "NEAT1 is significantly downregulated in the PMBCs of early-onset myocardial infarction (MI) patients, mainly in the cluster of differentiation-14-positive (CD14+) monocytes." (PMID 40362651, 2025). "The results showed that CGA pretreatment reduced myocardial infarction size and cTnT contents in serum, simultaneously reduced the levels of Lnc Neat1 expression and attenuated NLRP3 inflammasome-mediated pyroptosis in myocardial tissue." (PMID 37853132, 2023). "Previous studies have shown that Lnc Neat1 is a pivotal contributor to promoting MIRI and associated with the reduce of myocardial infarct size." (PMID 37853132, 2023). "Long noncoding RNA NEAT1 inhibits the progression of patients with early onset myocardial infarction by regulating the immune cell function." (PMID 35662687, 2022). "NEAT1 is overexpressed in the peripheral blood of patients with myocardial infarction and promotes hypoxia-induced cardiomyocyte injury." (PMID 34923910, 2022). "LncRNA AK139328 and lncRNA NEAT1, which were targeted miR-204-3p and Foxo1, respectively, enhanced autophagy by regulating Atg5 and Atg7 levels, which increased myocardial infarction size and aggravation of MIRI." (PMID 35370737, 2022). "RNA sequencing was conducted on peripheral blood mononuclear cells (PBMCs) of early onset myocardial infarction (MI) patients, and lncRNA nuclear enriched abundant transcript (NEAT1) was the most highly expressed lncRNA." (PMID 34084771, 2021). "In this context, lncRNA Neat1 was necessary for fibroblast and cardiomyocyte survival, and the silencing of Neat1 resulted in reduced heart function after myocardial infarction." (PMID 33808038, 2021). "NEAT1 affects cardiomyocyte proliferation and invasive metastasis by regulating the expression of the miR‐378‐3p/Atg7 axis, suggesting that NEAT1 may be a potential therapeutic target for myocardial infarction." (PMID 40032652, 2025). "Within the cardiovascular field, suppression of lncRNA NEAT1 was observed in circulating immune cells of post-myocardial infarction (MI) patients." (PMID 37998395, 2023). "In the cardiovascular field, suppression of lncRNA NEAT1 was observed in circulating immune cells of post-myocardial infarction (MI) patients." (PMID 36615135, 2023). "In the cardiovascular field, we observed suppression of lncRNA NEAT1 in circulating immune cells of post-myocardial infarction (MI) patients." (PMID 36552736, 2022). "However, one contradicting study reported decreased NEAT1 levels in peripheral blood mononuclear cells (PBMCs) of post-myocardial infarction (MI) patients and demonstrated enhanced inflammatory activation of macrophages in NEAT1-knockout mice." (PMID 37509544, 2023).
rheumatoid arthritis (21 papers, 2019 to 2025). A chronic, systemic autoimmune disorder characterized by inflammation in the synovial membranes and articular surfaces. "It has been observed in a rheumatoid arthritis study that NEAT1 is able to activate the ROCK2 and WNT pathway by inhibiting miR-144-3p." (PMID 38001964, 2023). "Like in MS, microarray analysis of lncRNAs revealed NEAT1 that was significantly upregulated in PBMCs and serum exosomes from patients with rheumatoid arthritis." (PMID 35796900, 2022). "NEAT1-miR-212-3p-TTK is reported to be a potential RNA regulatory pathway that controls disease progression in early Rheumatoid Arthritis." (PMID 36523600, 2022). "A recent study examining PBMCs from rheumatoid arthritis patients indicated that NEAT1 was elevated in Th17 cells and demonstrated that knockdown of NEAT1 inhibited Th17 differentiation." (PMID 31336952, 2019). "In addition, in rheumatoid arthritis, the exosome LncRNA NEAT1 can also promote the proliferation of CD4+ T cells and the differentiation of Th17 cells through the WNT signaling pathway, and aggravate the occurrence of bone destruction." (PMID 38107573, 2023). "In autoimmune diseases, a recent study has revealed that in rheumatoid arthritis, NEAT1 enhances cell proliferation, migration, invasion, and the release of inflammatory cytokines, produces higher S-to-G2/M phase transition, and inhibits apoptosis in fibroblast-like synoviocytes." (PMID 37343193, 2023). "These new findings bring us to think that by detecting the levels of genes that are highly expressed in the body, such as the exosomal Hotair and NEAT1 in rheumatoid arthritis, it may be possible to help clinicians better diagnose the disease." (PMID 38107573, 2023). "The in vivo delivery of a lentivirus to express a NEAT1 siRNA to target Th17 cells relieved RA in a type II collagen-induced mouse model of rheumatoid arthritis." (PMID 40362651, 2025). "NEAT1 reduces STAT3 levels, thereby blocking Th17 cell differentiation in PBMCs of rheumatoid arthritis patients." (PMID 37346034, 2023). "NEAT1 has also been found to target STAT3 and regulate the differentiation of Th17 cells in rheumatoid arthritis." (PMID 35069587, 2021). "Similarly, both NEAT1 and MALAT1 have been suggested as clinical outcome biomarkers in rheumatoid arthritis." (PMID 39337694, 2024). "Similarly, NEAT1 inhibits SIRT6 ubiquitination, promoting inflammation in rheumatoid arthritis." (PMID 41268533, 2025).
bladder cancer (20 papers, 2017 to 2024). "In this study, biotin-labelled NEAT1 variants were generated to incubate with cell lysate of bladder cancer cell T24 cells, and fished a batch of RNA substances." (PMID 35687898, 2022). "NEAT1 upregulation was associated with poorer recurrence-free survival of patients with bladder cancer." (PMID 36434587, 2022). "Overexpressed lncRNA NEAT1 results in cisplatin-resistance development in bladder cancer T24 cell line through WNT pathway activation." (PMID 38695942, 2024). "In conclusion, our data indicated that NEAT1 was expressed at high levels in bladder cancer patients and correlated with unfavourable prognosis." (PMID 36434587, 2022). "NEAT1 enhances bladder cancer cell lines proliferation and migration, and suppresses apoptotic effects." (PMID 36428492, 2022). "The effect of NEAT1 on the growth of bladder cancer in vivo was explored using an orthotopic tumourigenesis model." (PMID 36434587, 2022). "First, we incubated biotin-labelled NEAT1.1 and NEAT1.2 with cell lysate of bladder cancer cell T24 cells, and performed RNA pull down and next generation sequencing to investigate the binding RNAs with NEAT1." (PMID 35687898, 2022). "Additional research is needed to further explore the mechanism by which NEAT1 is involved in the development of bladder cancer." (PMID 36434587, 2022). "The promoting effects of NEAT1 on bladder cancer cells were reversed by miR-101 upregulation, and inhibition of miR-101 enhanced the effects of NEAT1." (PMID 36434587, 2022). "In vitro experiments explored the effects of NEAT1 on biological behaviours of bladder cancer T24 and 5637 cells." (PMID 36434587, 2022). "NEAT1 promoted malignant development of bladder cancer in vitro and in vivo by regulating the miR-101/VEGF-C pathway." (PMID 36434587, 2022). "In this section, we summarize and discuss the role of the NEAT1/miRNA/target axis in urinary system tumors, including bladder cancer and renal cell carcinoma." (PMID 34512157, 2021). "Furthermore, the notion that NEAT1 is a pro-lymphangiogenic lncRNA is also supported by an independent study demonstrating that NEAT1 upregulates VEGF-C expression in bladder cancer by sponging its negative regulator miR-101." (PMID 37407839, 2023). "The relationship between NEAT1 and the prognosis of patients with bladder cancer was analysed." (PMID 36434587, 2022). "Overexpression of NEAT1 promoted the proliferation, migration and invasion of bladder cancer cells." (PMID 36434587, 2022). "In bladder cancer, NEAT1 has played oncogenic roles and has been indicated as a therapeutic target." (PMID 33393590, 2021). "We know of no other study relating NEAT1 to CC risk, though a Chinese study found a relationship between NEAT1 and bladder cancer." (PMID 28423658, 2017). "Also, NEAT1 was reported conductive to the bladder cancer progression by the miR-410/HMGB1 axis." (PMID 32280304, 2020). "Similarly, NEAT1 targeted miR‐448 to enhance ZEB1 expression in bladder cancer." (PMID 32596993, 2020). "In the present study, the expression of NEAT1, miR-101 and VEGF-C was detected in human bladder cancer samples." (PMID 36434587, 2022). "NEAT1 and VEGF-C were significantly upregulated in bladder cancer samples, and miR-101 was significantly downregulated." (PMID 36434587, 2022). "However, detailed roles of NEAT1 in bladder cancer are largely unknown." (PMID 36434587, 2022). "In addition, the expression of NEAT1.1, an isomer of NEAT1, was significantly increased in bladder cancer cells, and OCT4 bound to and upregulated the expression of NEAT1.1 in bladder cancer cells sensitive to cisplatin treatment." (PMID 35907897, 2022).
systemic lupus erythematosus (20 papers, 2017 to 2025). An autoimmune multi-organ disease typically associated with vasculopathy and autoantibody production. "NEAT1 deficiency alleviated the symptoms of lupus and inhibited the activation of IFN-1 signaling in B cells of pristane-induced lupus mice, indicating that lncRNA NEAT1 plays a key role in the activation of B cell IFN-1 signaling pathway." (PMID 35003113, 2021). "In systemic lupus erythematosus, the expression levels of Lnc Neat1 is abnormally increased, and knockdown of Lnc Neat1 significantly reduces lipopolysaccharide (LPS)-induced inflammatory cytokine expression." (PMID 37853132, 2023). "LncRNA NEAT1 was highly expressed in G-MDSCs of lupus MRL/LPR mice, and G-MDSCs enhanced TLRs or IFN-α to produce BAFF." (PMID 35003113, 2021). "It has been shown that Neat1 functions as a novel inflammatory regulator acting through the MAPK pathway in human lupus." (PMID 33628632, 2021). "Neat1 expression is increased in Systemic Lupus Erythematosus and knockdown of Neat1 reduces cytokines such as IL-6 and CXCL1038." (PMID 31673072, 2019). "In lupus, over expression of lncRNA NEAT1 was reported to promote secretion of multiple pro-inflammatory cytokines and positively correlated with lupus disease activity." (PMID 30619325, 2018). "Upregulated NEAT1 expression has been observed in mononuclear cells of patients with systemic lupus erythematosus." (PMID 29463949, 2017). "Therefore, NEAT1 promotes Th2 cell activation through STAT6, supporting the observation that NEAT1 expression is induced in the PBMCs of systemic lupus erythematosus (SLE), which is primarily influenced by a Th2-mediated immune response." (PMID 40362651, 2025). "Intriguingly, NEAT1 has been recently identified as a novel inflammatory regulator in human lupus." (PMID 32089649, 2020). "They deduced that the differentially expressed lncRNAs (DE lncRNAs), myocardial infarction associated transcript (MIAT) and nuclear enriched abundant transcript -1 (NEAT1), and three novel miRs (hsa-miR-145, hsa-miR-17, and hsa-miR-143) play crucial roles in lupus pathogenesis." (PMID 33291347, 2020). "To validate the NEAT1/STING axis in vivo, we assessed STING expression in renal tissues of MRL/lpr lupus-prone mice." (PMID 41457558, 2025). "To establish the in vivo relevance of NEAT1 in LN pathogenesis, we employed the MRL/lpr lupus-prone mouse model." (PMID 41457558, 2025). "Notably, NEAT1 is highly expressed in peripheral blood mononuclear cells (PBMCs) of patients with SLE and negatively correlated with the Th1/Th2 ratio, thus influencing the progression of systemic lupus erythematosus." (PMID 35794862, 2022). "For example, lncRNAs, such as Hotair, LUST, anti-NOS2A, MEG9, SNHG4, TUG1, and NEAT1, have been found to be highly expressed in rheumatoid arthritis, while the expression of lnc-HSFY2–3:3 and lnc-SERPINB9–1:2 is reduced in systemic lupus erythematosus (SLE)." (PMID 38473997, 2024).